EGFR (epidermal growth factor receptor)
Diseases named in the same sentence as EGFR in open-access papers (continued):
Sharing a sentence is not in itself a finding about the gene and the disease.
breast carcinoma (continued). "These signatures include EpCAM for colorectal and ovarian cancers, epidermal growth factor receptor (EGFR) for brain cancers and human epidermal growth factor receptor 2 receptor (HER2/neu) for breast cancer." (PMID 26604322, 2015). "We conclude that the activity of AZD5363 in HER2-amplified breast cancer cells is enhanced by the addition of AZD8931 and that dual targeting of AKT and EGFR/HER2/HER3 signalling is an attractive treatment option to be explored in the clinic." (PMID 26095475, 2015). "EGFR and HER3 expression is substantially increased after long-term trastuzumab exposure of breast cancer cell lines to trastuzumab." (PMID 26498681, 2015). "Lapatinib, a dual epidermal growth factor receptor (EGFR) and HER2 tyrosine kinase inhibitor (TKI), has been approved for HER2-positive breast cancer patients." (PMID 26513016, 2015). "Since PTPH1 decreases EGFR/Y1173 phosphorylation, we next examined if PTPH1 requires its catalytic activity to sensitize breast cancer cells to TKIs." (PMID 26079946, 2015). "In breast cancer xenografts, the HER2 and EGFR expressed in the tumor tissues were identified using antibody conjugated F-SERS dots by the FRES in a minimally invasive procedure." (PMID 25820115, 2015). "In MDA-MB-231 breast cancer cells stably overexpressing H19, EGF strongly activated EGFR, Akt and Erk compared to parental cells." (PMID 26353930, 2015). "Five genes—CYP19A1, EGFR, ESR2, FOS, and IGF1—were common among all three EDCs–PCBs, phthalates and BPA, 17β-estradiol, breast cancer, and endometriosis." (PMID 26512648, 2015). "In HER2-postive breast cancer, it is possible that excessive activation of HER2 predominately controls the signaling pathway, thus masking the activation of EGFR signaling by Ano1." (PMID 25961581, 2015). "ER-α36 also physically interacts with EGFR and HER2 and promotes malignant growth of breast cancer cells." (PMID 26396174, 2015). "EGFR is involved in the induction of tamoxifen resistance and is known to activate the MAPK/ERK and PI3K/AKT pathways in breast cancer cells." (PMID 25990368, 2015). "About one-fourth of breast cancer patients express HER2 (human epidermal growth factor receptor-2), a transmembrane receptor tyrosine kinase of the epidermal growth factor receptor (EGFR) family." (PMID 26047322, 2015). "Given that STAT3 is a well-known key pathway downstream of EGFR and an EMT promoter in breast cancer, we infer that the possible mechanism through which Anxa2 promotes EMT is dependent on the STAT3 pathway." (PMID 26307676, 2015). "Paralleling effects on cell survival, AICAR leads to dose- and time-dependent inhibition of HER2 and EGFR in HER2-amplified breast cancer cells, with activation of AMPK and suppression of HER2/EGFR activity preceding commitment to cell death." (PMID 26143491, 2015). "EGFR is frequently overexpressed in triple-negative breast cancer (TNBC), a breast cancer type that is particularly aggressive and difficult to cure." (PMID 26025929, 2015). "A substantial increase in HGF and/or MET expression levels as a consequence of EGFR inhibition was shown to be responsible for the bypass of RTK inhibition in adult glioblastoma and breast cancer." (PMID 26496080, 2015). "Subsequently, a panel of human breast cancer cell lines was screened for Anxa2, EMT markers, and EGFR expression by Western blotting analysis." (PMID 26307676, 2015). "Cancers overexpressing receptor tyrosine kinases (RTKs) EGFR and/or HER2, particularly breast cancers, are known to be resistant to established chemotherapy." (PMID 26068969, 2015). "Breast cancer patients with ERBB2 amplifications are currently treated with lapatinib, a small-molecule kinase inhibitor that specifically blocks EGFR/ERBB2 signaling." (PMID 25596742, 2015). "In conclusion, our study demonstrates that Anxa2 expression is positively correlated with the expression of EGFR and EMT markers in breast cancer tissues and cell lines." (PMID 26307676, 2015).
breast carcinoma (continued). "Lapatinib, a small molecule dual inhibitor of EGFR and HER2, is another therapeutic option for HER2-positive breast cancer patients, although it offers only a 4.3% response rate in patients with HER2-positive breast cancer when used as monotherapy." (PMID 26143491, 2015). "Inhibition of EGFR and COX2 can decrease the lung metastatic progression in a clinically relevant model of breast cancer." (PMID 25598217, 2015). "NIR-PIT shows highly target specific cytotoxity, and NIR light can be easily applied to primary breast cancers transcutaneously, therefore NIR-PIT is a promising method of treating EGFR expressing TNBC." (PMID 26313651, 2015). "Among breast cancer cell lines, MCF7 is unique when the measure crs(h = 2) is used to assess the EGFR pathway with GRB2 and MAPK1 ranking highest, while all the other cell lines have EGFR and/or RAF1 as top ranking genes." (PMID 24550933, 2014). "Continued research into the role of the Notch pathway in tumorigenesis has revealed novel crosstalk with the EGFR and HER2 receptors in a variety of solid tumors, including breast cancer." (PMID 25566499, 2014). "In breast cancer, HER2 amplification is used to guide the use of trastuzumab, an antibody to HER2, and lapatinib, a dual EGFR and HER2 small molecule targeted agent." (PMID 24964744, 2014). "Previous study showed that AZD8931 is an equipotent, reversible inhibitor of EGFR, HER2 and HER3 signaling with potent in vitro inhibition of EGFR, HER2 and HER3 phosphorylation in breast cancer and squamous carcinoma cells." (PMID 24886365, 2014). "We stimulated SKBR3 breast cancer cell lines with EGF and observed peak activation of EGFR signalling at 5 minutes." (PMID 24523872, 2014). "Here, we studied the estrogen and anti-estrogen sensitivity of human breast cancer MCF7 cells that have a moderate, retroviral-mediated, ectopic expression of epidermal growth factor receptor (MCF7-EGFR)." (PMID 24758408, 2014). "Lapatinib, a dual EGFR/HER2 tyrosine kinase inhibitor, has been shown to improve the survival rate of patients with advanced HER2-positive breast cancers." (PMID 24707474, 2014). "HER-2 is a member of the epidermal growth factor receptor (EGFR) family, which has also been used to predict the prognosis of breast cancer." (PMID 25120655, 2014). "For example, the top 12 cell lines include fivepancreatic, three ovarian and four breast cancer cell lines, of which three are basal subtype andone, HCC-1954, is EGFR-high/Her2 amplified." (PMID 24987113, 2014). "More recently, the extracellular domain of soluble E-cadherin was shown to interact with EGFR and activate EGFR-mediated PI3K/AKT and ERK1/2 signalling in breast cancer cells and squamous cell carcinoma." (PMID 25164084, 2014). "HER2 is a member of the EGFR/ERBB family of RTKs, best known for its role in breast cancer, where it is targeted by the antibody trastuzumab." (PMID 24722523, 2014). "When the gene expression profile of 1,5-isoquinolinediol across 4 breast cancer cell lines is compared to the other 1300 drugs available in MANTRA, the most similar gene expression signature is the one corresponding to the EGFR tyrosine kinase drug gefitinib." (PMID 24632590, 2014). "In particular, the ligand activation of the EGFR transduction pathway was shown to trigger GPER expression in both ER-negative and -positive breast cancer cells." (PMID 24834064, 2014). "Although the luminal breast cancer lines MCF7 and T47D expressed very low levels of total EGFR, they exhibited significant EGFR phosphorylation." (PMID 25361177, 2014).
breast carcinoma (continued). "Our study only shared three inhibitors with the previous study which target MEK or EGFR and our results are in agreement that TNBC cell lines are more sensitive to these inhibitors than luminal breast cancer cell lines." (PMID 24762669, 2014). "As a third application case, we selected data for a set of 26 breast cancer cell lines from the CCLE resource and studied their differential responses to lapatinib, a clinically approved dual EGFR and ERBB2 (HER2) kinase inhibitor." (PMID 24898935, 2014). "In a prior study, it was reported that dasatinib inhibited EGFR, HER-2 and HER-3 expression in breast cancer cells, specifically the cell lines MDA-MB-468, SKBR3, MDA-MB-453, and MDA-MB-231." (PMID 24979294, 2014). "Here, we showed that stem-like cells in the tumorspheres derived from MCF7 express elevated levels of ER-α36, EGFR and HER2, indicating there exist the ER-α36-EGFR/HER2 regulatory loops in the ER-positive breast cancer stem/progenitor cells." (PMID 25203051, 2014). "In this research, three types of human breast cancer cell cultures of MDA-MB-468 (1 × 106 EGFR/cell), MDA-MB-231 (2 × 105 EGFR/cell), and MCF-7 (1 × 104 EGFR/cell) were used." (PMID 25379530, 2014). "To investigate the cell signaling status of various direct and indirect targets of erlotinib and metformin in BBCs, we examined the phosphorylation levels of EGFR, AMPK, AKT, S6 and 4E-binding protein 1 (4EBP1) in a panel of breast cancer cell lines." (PMID 25361177, 2014). "The genetic and pharmacological inhibition of ERBB3 results in anti-tumorigenic activity in cancer cells, both in vitro and as xenograft, and sensitizes lung cancer cells and breast cancer cells to lapatinib, a dual TKI of EGFR and ERBB2." (PMID 24970817, 2014). "Lapatinib, a reversible dual-kinase inhibitor of epidermal growth factor receptor (EGFR) and HER2, has activity in HER2-overexpressing breast cancer and is approved in combination with capecitabine for the treatment of patients with metastatic disease." (PMID 25186428, 2014). "Our data thus suggested that elevated ER-α36 expression is involved in enhanced expression of EGFR and HER2 in TAM resistant breast cancer cells." (PMID 25203051, 2014). "EGFR, HER-2, and c-Met are among the most critical proteins for breast cancer proliferation and survival." (PMID 24849787, 2014). "Our results demonstrate for the first time that CXCR7 interacts with EGFR in human breast cancer cell lines and that CXCR7-EGFR co-localization is significantly increased upon EGFR over expression." (PMID 25168820, 2014). "Additional studies by this group determined that co-inhibition of PI3K and EGFR suppressed growth and PI3K signaling in human breast cancer cells containing the mutant PIK3CA-H1047R gene." (PMID 25051360, 2014). "In particular, EGFR is frequently overexpressed in TNBC, a subset of breast cancer that is characterized by their unique molecular profile, aggressive behavior and distinct patterns of metastasis." (PMID 24575839, 2014). "In this study we created human breast cancer MCF7 cells that ectopically express human EGFR (MCF7-EGFR) with a 3-fold induction compared to wild type MCF7 cells, allowing the study of EGFR exclusively in the context of anti-estrogen activity of tamoxifen." (PMID 24758408, 2014). "We established a TAM-resistant breast cancer cell line MCF-7/TAM, of which ER-α36 and EGFR were both overexpressed while ER-α66 was down-regulated comparing to parental MCF-7 cells." (PMID 24447535, 2014). "Although the majority of clinical benefits from lapatinib-based treatment were observed in patients with HER2-positive breast cancers, there are still several clinical trials of lapatinib in HER2-negative patients due to its EGFR inhibition activity." (PMID 24707474, 2014).
breast carcinoma (continued). "Metformin has been shown to reduce EGFR, mitogen-activated protein kinase (MAPK) and AKT signaling in breast cancer cell lines, and selectively induced apoptosis in TNBC cells." (PMID 25361177, 2014). "Nevertheless, contribution of the HERs in breast cancer progression is complex, and studies have focused more specially on HER3/HER2 or HER2/EGFR dimers." (PMID 25249538, 2014). "Lapatinib is a tyrosine kinase inhibitor that targets the intracellular domain of HER2 and EGFR and is approved for the treatment of HER2-positive breast cancer." (PMID 24639951, 2014). "The involvement of EGFR in Prl-R signaling is supported by previous findings of the interplay between EGF and Prl in breast cancer cells." (PMID 24695557, 2014). "Previous reports have shown that Bad in breast cancer cells or Bim in NSCLC can integrate the MAPK and AKT signals for cell survival and death in the EGFR blockade." (PMID 24970817, 2014). "Concerning the possible link between FGF/FGFR and drug resistance to EGFR-TKIs, we have previously demonstrated amplification of the FGFR2 gene in lapatinib-resistant breast cancer cells." (PMID 25115383, 2014). "MSCs express functional epidermal growth factor receptor (EGFR) and breast cancer cells secrete EGFR-ligands including transforming growth factor-α (TGFα)." (PMID 25344915, 2014). "Our data suggested that co-inhibition of EGFR and IGF-1R synergistically radiosensitized breast cancer cells with both EGFR and IGF-1R high expression." (PMID 23777562, 2013). "Twenty four FMAs were classified according to the current human histologic breast cancer classification including immunohistochemistry (IHC) for ER, PR HER2, CK5/6 and EGFR." (PMID 24004841, 2013). "Our current study presents a novel role of PEITC in preventing and suppressing breast cancer metastasis in vivo possibly by suppressing HER2, EGFR and VEGF, which are known to promote cell motility." (PMID 23826254, 2013). "The MCF-7 (EGFR +/−, IGF-1R +++) and MDA-MB-468 (EGFR +++, IGF-1R +++) breast cancer cell lines were used." (PMID 23777562, 2013). "The mutational and mRNA expression status of PIK3CA, PIK3R1 and AKT1, and expression status of other genes involved in the PI3K pathway (EGFR, PDK1, PTEN, AKT2, AKT3, GOLPH3, WEE1, P70S6K) were assessed in a series of 458 breast cancer samples." (PMID 24229379, 2013). "Although lapatinib is considered an equipotent inhibitor of HER2 and EGFR, based on data from in vitro kinase assays, its clinical efficacy to date has been limited to HER2+ breast cancers." (PMID 24044505, 2013). "To examine this long-range interaction in more detail, we labeled gene pairs EGFR and IGFBP3 by 3D-FISH in HMEC and breast cancer cell lines MCF7 and MDA-MB-231." (PMID 24019942, 2013). "Lapatinib, a dual epidermal growth factor receptor (EGFR) and human epidermal growth factor receptor 2 (HER2) kinase inhibitor, is used for the treatment of advanced HER2-positive breast cancer." (PMID 23965981, 2013). "Primary tumors (PTs) of breast cancer and corresponding metastases (MTs) were used to evaluate the expression of GPR30 and epidermal growth factor receptor (EGFR) immunohistochemically." (PMID 24289103, 2013). "The purpose of this study was to classify FMAs according to the current human classification of breast cancer that includes evaluation of ER, PR and HER2 status and expression of basal CK 5/6 and EGFR." (PMID 24004841, 2013). "Katz has reported that activation of AKT by CDDP is dependent of SRC, EGFR and PI3K, which can be placed in one signal transduction pathway, with EGFR and SRC upstream of PI3K in breast cancer." (PMID 23533654, 2013). "For example, hormone receptors (ER and PR), growth factor receptor (HER2, EGFR, and IGF-1R), and angiogenic factors (VEGFR, integrin αvβ3) have been adopted as imaging targets to detect/stage the breast cancer and monitor treatment efficacy." (PMID 23533377, 2013).
breast carcinoma (continued). "This pattern is consistent with gefitinib directly promoting formation of inactive EGFR-based homodimers or heterodimers (EGFR/HER2, EGFR/HER3) in several breast carcinoma cell lines." (PMID 23748900, 2013). "There were about 65% with the overexpression of EGFR and 22.5% with the overexpression of IGF-1R in basal-like breast cancer patients." (PMID 23777562, 2013). "Among the significant intrachromosomal interactions common to all samples, and across all window sizes, was an interaction with epidermal growth factor receptor (EGFR), another breast cancer related gene." (PMID 24019942, 2013). "By integrative functional genomics investigation, we identified the involvement of EGFR, RAS, PI3K / AKT, MYC, E2F signaling in the regulation of these selected 1q genes in breast tumors and breast cancer cell lines." (PMID 24147022, 2013). "For example, the EGFR tyrosine kinase inhibitor (TKI) gefitinib has been extensively investigated and studies suggested that this drug can be effective against breast cancers expressing EGFR, especially in the background of HER2 overexpression." (PMID 24146879, 2013). "We found that expression of IGF1-R was present in 38.5%, FGFR2 in 12.1%, EGFR in 11.4%, HER2 in 3.0%, and MET in 4.5% of male breast cancers." (PMID 23308200, 2013). "In breast cancer MTs, GPR30 expression significantly increased relative to corresponding PTs and correlated with EGFR expression." (PMID 24289103, 2013). "This dual-kinase inhibitor which also targets EGFR was developed by GlaxoSmithKline (GSK) and is currently FDA approved for the treatment of refractory breast cancer in combination with capecitabine." (PMID 23816254, 2013). "A potential panel of markers for molecular imaging, consisting of EGFR, IGF1-R, FGFR2, CD44v6, CAXII, GLUT1, and CD44v6 was positive in 77% of male breast cancers, comparable to female breast cancers." (PMID 23308200, 2013). "Targeting EGFR hyperactivity and PI3K/AKT pathways have been the therapeutic approach for the treatment of breast cancer." (PMID 24059654, 2013). "Nonetheless, our observations raise the possibility of distinct treatment strategies in SYK-positive SCLC tumors, by analogy to lung tumors overexpressing EGFR, or HER2+ breast cancers, whose response to targeted therapy dramatically improves the outcome." (PMID 24564859, 2013). "A number of studies have evaluated the efficacy of lapatinib, a small molecule tyrosine kinase inhibitor that targets both EGFR and HER2, in the setting of HER2-positive breast cancer brain metastases." (PMID 23662165, 2013). "Gefitinib induces formation of inactive EGFR/HER2 and EGFR/HER3 heterodimers in HER2-overexpressing breast cancer cells." (PMID 23748900, 2013). "EGFR positivity is reported to be a worse prognostic factor, and is also reported to be high in HER2 positive breast cancer." (PMID 24245483, 2013). "In 53 human breast cancer specimens, GPR30 expression in MTs increased compared to matched PTs; in MTs, the expression patterns of GPR30 and EGFR were closely related." (PMID 24289103, 2013). "Previous studies reported that histone deacetylase inhibitor (HDACi) LAQ824 reduced EGFR and HER2 expression in breast cancer cells." (PMID 23922886, 2013). "Our previously proposed panel consisting of CD44v6, EGFR, HER2, IGF1-R, and GLUT1 for imaging of female breast cancer was significantly less sensitive for imaging of male breast cancer (female breast cancer 79.3% vs. male breast cancer 69.1%, p = 0.025)." (PMID 23308200, 2013). "Herceptin (Trastuzamab), a humanised IgG1 antibody targeted against the human epidermal growth factor receptor (HER2), is widely used for the treatment of breast cancer." (PMID 23859937, 2013). "TAM number and EGFR expression levels correlate in human breast tumors, and TAM induce the EGFR-dependent migration of tumor cells in a murine breast carcinoma model." (PMID 23597096, 2013).